IL6 (interleukin 6)
Diseases named in the same sentence as IL6 in open-access papers (continued):
Sharing a sentence is not in itself a finding about the gene and the disease.
neuroblastoma (continued). "However, it has been shown that the protein IL6 is able to stimulate C9 mRNA expression in post-mortem human astrocytes and neuroblastoma cells, showing a metabolic link between the two proteins in the cells of the nervous system." (PMID 26626881, 2015). "In neuroblastoma, IL6 enhanced cell survival in cells cultivated in serum-deprived media." (PMID 26215971, 2015). "In neuroblastoma IL6 protects cells from drug-induced apoptosis and increases proliferation." (PMID 26215971, 2015). "IL-6, which is secreted by mononuclear phagocytes in response to neuroblastoma cells, and TGFβ1, which is secreted by both tumor cells and mononuclear phagocytes in response to neuroblastoma cells, suppress the activation of NK cells by IL-2." (PMID 23982484, 2013). "Because of these clinical and preclinical effects, we hypothesized that lenalidomide also could prevent the suppression of IL-2 activation of NK cells by neuroblastoma/monocyte CM, IL-6, and TGFβ1." (PMID 23982484, 2013). "Interestingly, SPON1 has been shown to be upregulated in several cancers, including neuroblastoma and chondrosarcoma, and it has also been found to have a role in promoting neuroblastoma by leading high IL-6 expression through the MEKK/p38 MAPK/NF-κB–dependent pathway." (PMID 38716730, 2024). "In addition, IL-6 prevents etoposide- and melphalan-induced apoptosis in neuroblastoma." (PMID 38438872, 2024). "We evaluated the expression of HERVs (HERV-K env, HERV-K gag, HERV-W env, and HERV-H env) and cytokine gene expression (IL-1, IL-6, and TNF-α) in neuroblastoma (SH-SY5Y), HEp-2, and Caco-2 cell lines under simulated μg and 1g conditions." (PMID 40143237, 2025). "CT exposure downregulates mitochondrial oxygen consumption rate in neuroblastoma SH-SY5Y cells, increases IL-6, SOD1, and TNFα expression, and enhances cell apoptosis." (PMID 41424770, 2025). "We found significant differences in the serum levels of IL-1β, IL-6, IL-12p40, IL-12p70, TNF-α, IFN-γ, IL-8 and MCP1 between patients with neuroblastoma and the control group." (PMID 40722593, 2025). "The analysis of the secretome induced by TRT revealed that neuroblastoma cells (SK-N-BE) treated with 131I-MIBG produced ROS, interleukin-6 (IL-6), and tumor necrosis factor-α (TNF-α)." (PMID 40725216, 2025). "In neuroblastoma SH-SY5Y cells, previous studies observed that LPS treatment resulted in the enhanced synthesis of proinflammatory cytokines like TNF-α, IL-1β, and IL-6, while there was a decrease in anti-inflammatory cytokines like IL-10." (PMID 38671881, 2024). "A previous study has reported that in the microenvironment of human neuroblastoma, GAL‐3BP interacts with GAL‐3 in bone marrow mesenchymal stem cells and induces transcriptional upregulation of IL‐6, via the Gal‐3BP/Gal‐3/Ras/MEK/ERK signaling pathway." (PMID 37567864, 2024). "Treatment of the AD SH-SY5Y (human neuroblastoma cells) cell model with DPEO resulted in decreased intracellular levels of Aβ, GSK-3β, P-Tau, IL-1β, TNF-α, IL-6, COX-2, OFR, and HFR, alongside reduced AchE and BchE activities and increased SOD activity." (PMID 39056736, 2024). "PS suppressed the levels of IL-6, IL-10, CXCL1, and CXCL2 induced by paclitaxel in a neuroblastoma cell line, and macrophage activation to the M1 proinflammatory phenotype." (PMID 38347876, 2023). "We tested the effect of exposing human neuroblastoma SH-SY5Y cells to IL-1β, TNF-α, and IL-6 on thiamin uptake." (PMID 35750148, 2022). "Transfection of shTHRIL was performed in human neuroblastoma SH-SY5Y cells, followed by the detection of the levels of IL-6, IL-1β, and TNFα." (PMID 33675584, 2021). "Experimentally, we have shown that neuroblastoma cells stimulate blood monocytes to secrete IL-6 and that TAMs stimulate the growth of neuroblastoma cells in NOD/SCID mice, at least partially via IL-6 secretion." (PMID 23982484, 2013).
neuroblastoma (continued). "Biochemical evidence demonstrates that in primary cortical neurons and SH-SY5Y neuroblastoma cells, IL-6 cytokine family members, OSM and IL-6 plus the soluble IL-6R (IL-6/R), prevent NMDA and glutamate-induced neuronal toxicity." (PMID 23226414, 2012). "Although the concentrations of human exposure to CT vary, our data suggest that even at low concentrations of acute exposure to MC-LR, NOD, CYN, and BMAA change cell metabolic activities, increase inflammatory IL-6, SOD1, and TNFα gene expression, and cytotoxicity in neuroblastoma cells." (PMID 41424770, 2025). "In line with that, in an in vivo study, sulforaphane was observed to reduce inducible nitric oxide synthase (iNOS), proinflammatory levels (IL-1β, IL-6), cyclooxygenase-2 (COX-2), and nuclear factor (NF)-κB p-p65 in mouse neuroblastoma N2a cells expressing APPswe." (PMID 39493676, 2024). "In co-cultured murine neuroblastoma and microphage cell lines (Neuro-2A and RAW264.7) that mirror the inflammatory infiltrate of CIPN, we evaluated the effect of PS on the expression of four cytokines, IL-6, IL10, CXCL-1, and CXCL-2, all involved in CIPN." (PMID 38347876, 2023). "In addition, SPON1 was shown to promote survival in a murine neuroblastoma model under stressful conditions via a p38 MAPK dependent pathway, ultimately upregulating IL‐6 expression." (PMID 35487760, 2022). "A subsequent study confirmed that higher levels of TAM-specific genes (CD14, CD16, IL6, IL6R and TGFB1) were associated with a worse prognosis in MYCN-nonamplified neuroblastomas." (PMID 26729169, 2015). "Our results suggest that the serum levels of pro-inflammatory cytokines IL-6, IL-8, IFN-γ and TNF-α could be an immunological biomarker contributing to our understanding of the pathogenesis of neuroblastoma with prognostic potential in Mexican pediatric patients with NB." (PMID 40722593, 2025). "Thus, the fusion of anti-VEGF, anti-IL-6, or anti-IL-10R into the CAR structure may also be effective against neuroblastoma." (PMID 33322408, 2020). "Interestingly, CD68-positive TAMs co-expressing IL-6 was identified in the metastatic bone marrow samples of non-MYCN-amplified neuroblastoma." (PMID 32983125, 2020). "The inflammatory factor IL6 secreted by bone marrow mesenchymal stem cells (BMSCs) in the tumor microenvironment (TME) facilitates the survival and therapeutic resistance of neuroblastoma (NB)." (PMID 34790130, 2021). "However, inhibition of STAT3 activation significantly retards TAMs mediated tumor growth in subcutaneous neuroblastoma in mice, which suggests that IL-6 is not the key to the growth of neuroblastoma and may be related to the type of tumor." (PMID 33224886, 2020). "Sage even increased MCP-1, IL-6, IL-8 and ICAM-1 highly significantly in neuroblastoma (SK-N-SH) cells in a non-IL-1β treated group in 4 h and MCP-1 and ICAM-1 in 24 h." (PMID 39408750, 2024). "Upon activation with R848, a significantly increased secretion of IL6 was observed in the cocultures performed with the MYCN-nonamplified cell lines AS and SH, while IL6 secretion was enhanced after LPS activation in cocultures with the four neuroblastoma cell lines." (PMID 36923280, 2022).
sleep disorder (93 papers, 2012 to 2025). A change from the patient's baseline sleeping pattern, in the hours slept and/or an alteration/dysfunction in the stages of sleep. "Inflammatory markers, such as C-reactive protein (CRP) and interleukin-6 (IL-6), are closely associated with sleep disorders." (PMID 40894321, 2025). "Mechanistically, sleep disorders are known to promote systemic inflammation, elevating levels of C-reactive protein and interleukin-6, which are associated with increased mortality risk." (PMID 40290660, 2025). "Various studies show an association between sleep disorders and altered levels of inflammatory cytokines, especially IL-6." (PMID 37489445, 2023). "Research has reported that sleep disturbances are positively associated with inflammation and blood concentration of inflammatory markers, such interleukin-6 was higher in people with poorer sleep as compared with people with good sleep." (PMID 35356724, 2022). "An analysis shows the relationship between these salivary biomarkers and sleep quality, especially in the case of IL-6 in both healthy subjects and several pathologies associated with sleep-disorders." (PMID 33579032, 2021). "Both short sleep and sleep disturbances are associated with increased levels of pro-inflammatory biomarkers such as interleukin-1 (IL-1), interleukin-6 (IL-6) and tumor necrosis factor (TNF)." (PMID 33042933, 2020). "Similarly, sleep disturbances are associated with reduced growth hormone production and elevated levels of inflammatory cytokines, such as IL-6 and TNF-α, which contribute to poor wound healing outcomes." (PMID 40687576, 2025). "Interleukin-6 and interleukin 1β are implicated in various pathological processes in CTDs, and polymorphisms in genes encoding these cytokines have been associated with sleep disorders." (PMID 38999222, 2024). "As for sleep disorders, they were associated with the inflammatory factor IL-6 in one study." (PMID 35740389, 2022). "Thus, itcan be seen that sleep disorders can significantly impact immune system functionsince sleep deprivation is directly associated with an increase in pro-inflammatorycytokines, such as IL-6 and TNF-α, and a decrease in circulating killercells." (PMID 36158715, 2022). "Furthermore, two population-based studies found that consumption of red and processed meat has been associated with circulating inflammation markers, including C-reactive protein and interleukin-6, which have been linked to sleep disorders." (PMID 31011478, 2019). "Sleep disorders are also associated with an increased systemic immune and inflammatory dysregulation, mainly due to hyperexpression of pro-inflammatory mediators and cytokines (e.g., IL-1β, IL-2, IL-6, TNF-α, IL-18, sTNF-R1, and sTNF-R2), and intermittent hypoxia-induced oxidative stress." (PMID 41156291, 2025). "Furthermore, sleep disorders may exacerbate chronic inflammation in the gallbladder, with elevated inflammatory markers such as interleukin-6 (IL-6) and C-reactive protein (CRP) being associated with increased gallstone risk." (PMID 40313242, 2025). "In addition, inflammation markers, particularly interleukin-6, may be associated with suicidal risk in patients with sleep disorders." (PMID 34073804, 2021). "Thus, our data indicate that the IL-1β-31TT genotype and the APOEε4 allele were associated with sleep disturbances in AD patients and that these two SNPs synergistically enhanced LPS-induced IL-1β, IL-6 and TNF-α overexpression in white blood cells from AD patients with sleep disturbances." (PMID 26937653, 2016). "Sleep disorders further exacerbate healing delays by disrupting growth hormone secretion and increasing the release of inflammatory cytokines (e.g., IL-6, TNF-α)." (PMID 40687576, 2025). "Increase levels of inflammatory mediators such as Interleukin-6 and Tumor Necrosis Factor-alpha have also been shown in patients with sleep disorders." (PMID 40710903, 2025).
sleep disorder (continued). "For instance, evaluated levels of systemic inflammatory markers such as interleukin-6 (IL-6), C-reactive protein, and tumor necrosis factor were observed in individuals with sleep disorder." (PMID 40270512, 2025). "Sleep disorders can induce chronic pain in patients with orofacial pain due to an inflammatory imbalance characterised by elevated IL-6 production." (PMID 41459132, 2025). "In the acute phase of cerebral ischemia, the proliferation and activation of microglia led to a robust inflammatory response, characterized by increased levels of TNF and IL-1β and upregulation of IL-6, which can result in sleep disorders." (PMID 38671959, 2024). "Approximately fifty percent of the studies that analyzed IL-6 levels showed an increased elevation of IL-6 levels during the day in people with sleep disorders." (PMID 37489445, 2023). "Although some research has shown that sleep deprivation and sleep disorders increase daytime plasma IL-6 levels in adults, most studies relating IL-6 to sleep have measured IL-6 in blood and not in saliva." (PMID 37489445, 2023). "Increased gut microbiota-derived lipopolysaccharide (LPS) contributes to the production of proinflammatory cytokines such as IL-1β, TNF-α, and IL-6, which have been shown to play a key role in sleep disturbances." (PMID 36190400, 2022). "Further studies have established a bidirectional link between inflammatory biomarkers, such as C-reactive protein (CRP) and interleukin-6 (IL-6 and), and sleep disorders." (PMID 35768855, 2022). "The previous study found that, compared with non-drinkers, people who drank ≥4 cups of total coffee/day had lower concentrations of C-reactive protein and interleukin 6 (IL-6), which are related to sleep disorders." (PMID 35215524, 2022). "It seems that sleep disorders are associated with an increase in body inflammation, expressed by an increase in C-Reactive Protein (CRP) and Interleukin-6 (Il-6) concentration." (PMID 33153051, 2020). "With respect to inflammatory cytokines, a longitudinal study including nearly 3,000 participants reported that sleep disturbances (indexed by 6 components, such as sleep onset and sleep maintenance problems) predicted IL-6 levels measured 5 yr later." (PMID 30920354, 2019). "Sleep disorders promote a low-grade inflammatory status by increasing circulating proinflammatory cytokines (IL-1β, IL-6, IL-17A, TNF-α) and CRP." (PMID 30402295, 2018). "The patients with sleep disorders were examined with a series of complex cognitive tests, and it turned out that they had significantly larger IL-6 responses to the cognitive stressors in comparison with participants with no reported sleep problems." (PMID 26649857, 2017). "First, inflammatory cytokines, such as interleukin-1 and interleukin-6, have been shown to be significant contributors to sleep disturbances." (PMID 26222511, 2015). "Additional research is warranted to evaluate the relationship between this SNP (IL6 rs2069849) and a variety of sleep disturbances and sleep disorders." (PMID 22844404, 2012). "In addition, sleep disturbances and cognitive dysfunction are independently associated with increased inflammatory markers such as c-reactive protein (CRP) and interleukin-6 (IL-6)." (PMID 40898257, 2025). "For BMI, studies have showed that an increase of 6 units BMI can resulted in four time greater risk of OSA, specifically, The disruption of pro-inflammatory factors (e.g., IL-6, IL-12, TNF-α) caused by excessive visceral fat has been identified as a significant risk factor for sleep disorders." (PMID 40034171, 2025). "For example, prolonged exposure to elevated IL-6 levels in sleep disorders may disrupt the balance between pro-inflammatory and anti-inflammatory responses, thereby impairing the immune system’s ability to effectively recognize and eliminate cancer cells." (PMID 39120277, 2024).
sleep disorder (continued). "The increase in pro-inflammatory cytokines including interleukin (IL)-1, IL-6, IL-8, IL-17 and tumor necrosis factor, in turn, may affect the brain and contribute to the etiopathogenesis of sleep disorders." (PMID 39396146, 2024). "Indeed, it was observed that obese subjects had higher levels of IL-6 and TNF-α during the morning vs. the night, which was associated with sleep disorders and BMI." (PMID 39716153, 2024). "Disruption of circadian rhythm due to sleep disorders in PWH may lead to immune system dysregulation, resulting in elevated levels of inflammatory molecules, such as interleukin 6 and C-reactive protein, that have been associated with the risk of frailty." (PMID 38033984, 2023). "This could also be because women tend to have higher C-reactive protein (CRP) and interleukin-6 levels, which act as markers in the etiology of frailty A large number of older adults who had sleeping disorders were also found to be frail." (PMID 37438687, 2023). "A systematic review examining inflammation and sleep disorders noted that two inflammatory factors, C-reactive protein (CRP), and IL-6, are strongly associated with sleep disorders, which upregulate the expression of NF-κB and increase the levels of intercellular adhesion molecules." (PMID 38074156, 2023). "Serum IL-6 levels were significantly higher in the three sleep disorder groups than the control group at 6 h and 24 h after the operation (all P < 0.05), while group C has the highest IL-6 levels as compared to the other group (P = 0.09 and P < 0.001, respectively)." (PMID 36570021, 2022). "Moreover, sleep disorders impair the immune response and cause systemic inflammation by the dysregulation of substances such as TNF-α, IL-1β, and IL-6." (PMID 36188174, 2022). "Several studies have reported that sleep disturbances can increase systemic IL-6 concentrations." (PMID 35815027, 2022). "For example, sleep disturbances are associated with higher levels of C-reactive protein (CRP) and interleukin-6 (IL-6), which are also commonly elevated in musculoskeletal and neuropsychiatric diseases, and among people with a fast accumulation of chronic diseases." (PMID 33280611, 2020). "A recent meta-analytic review concluded that sleep disturbances show a stronger association with inflammatory upregulation (i.e., CRP and IL-6) than short sleep duration, supporting the importance of a better understanding of the inflammatory consequences of disturbed sleep." (PMID 30920354, 2019). "Patients with sleep disorders due to acute cerebral infarction displayed increased inflammatory factors, including C-reactive protein (CRP), IL-6, IL-1β, TNF-α and Hcrt, compared with normal levels." (PMID 38671959, 2024). "In fact, a prior meta-analysis has demonstrated that sleep disorders and insufficient sleep have elevated levels of c-reactive protein (CRP) and interleukin-6 (IL-6)." (PMID 38408934, 2024). "In line with this, a meta-analysis of 72 studies found a significant relationship between increased levels of IL-6 and CRP with sleep disorders." (PMID 38541200, 2024). "Certain cytokines, including IL-6, IL-1α, and tumor necrosis factor (TNF-α), exhibit notable circadian oscillations when they enter the brain, leading to sleep disorders." (PMID 39418274, 2024). "Inflammatory cytokines such as IL-1β, IL-6, and TNF-α, which are elevated in both sleep disorders and cancer, play a critical role in immune dysregulation." (PMID 39120277, 2024). "Sleep disorders, including RBD and ESS, exhibit significantly altered levels of IL-6, CRP, IL-1β, sTREM2, CCL3 and NO, suggesting these markers represent potential markers in PD patients." (PMID 36739284, 2023). "Increasing evidence has shown that elevated levels of inflammatory cytokines like IL-6 and TNFα were found in adults with MDD and people with sleep disorders." (PMID 37034932, 2023). "Several studies reported that IL-6 and TNF-α significantly increase in patients with sleep disorders." (PMID 36570021, 2022).